SPRR3 (small proline rich protein 3)
Description:
Cross-linked envelope protein of keratinocytes.
Tractability: Antibody: its Gene Ontology location is reachable by antibodies, with high confidence.
Gene: Protein-coding gene on chromosome 1 (153,001,747 to 153,003,856, forward strand). Ensembl gene ENSG00000163209.
Subcellular location: Cytoplasm
Pathways (Reactome):
Developmental Biology: Formation of the cornified envelope
Gene Ontology:
Molecular function: protein binding; structural molecule activity
Biological process: epidermis development; keratinocyte differentiation; wound healing
Cellular component: extracellular exosome; Golgi apparatus; perinuclear region of cytoplasm; cornified envelope; cytosol; cytoplasm
Genetic constraint (gnomAD): Loss-of-function variants: 1 observed, 1.26 expected, observed/expected ratio (o/e) 0.8, 90% interval 0.23 to 1.87. That is too few expected variants to judge how well the gene tolerates losing a copy. Missense variants: 183 observed, 207.37 expected, observed/expected ratio (o/e) 0.88, 90% interval 0.78 to 1. Synonymous variants: 58 observed, 73.9 expected, observed/expected ratio (o/e) 0.78, 90% interval 0.63 to 0.98.
Homologues: Orthologues: chimpanzee SPRR3 (92% identical), macaque SPRR3 (86% identical), rabbit SPRR3 (62% identical), rat Sprr3 (62% identical), mouse Sprr3 (60% identical). Paralogues in human: SPRR1B (40% identical), SPRR1A (39% identical), SPRR4 (24% identical), SPRR2G (20% identical), PRR9 (18% identical), KPLCE (15% identical), LCE2D (14% identical), LCE2A (13% identical), LCE2C (13% identical), LCE2B (12% identical), LCE5A (12% identical), LCE1E (12% identical), and 8 more.
Diseases named in the same sentence as SPRR3 in open-access papers:
SPRR3 is named in the same sentence as 59 diseases in open-access papers, as found by Europe PMC text mining. Sharing a sentence is not in itself a finding about the gene and the disease. The quoted sentences say what the papers report.
esophageal cancer (5 papers, 2014 to 2024). A primary or metastatic malignant neoplasm involving the esophagus. "C-Jun increased the promoter activities of cystatin A, involucrin, and SPRR3 in a dose-dependent manner, suggesting that c-Jun activates the promoters of these differentiation-associated genes in vivo in esophageal cancer cell line." (PMID 24796531, 2014). "Interestingly, proteomic analysis of ASCL2OE organoids showed altered expression of SPRR3, a protein that has been associated with resistance to DNA damage inducers in esophageal cancer cells." (PMID 38252116, 2024). "Current evidence suggests that SPRR3 expression is low in HNSCC26 and esophageal cancer, while other studies have substantiated that SPRR3 is a prognostic factor of esophageal cancer and a sensitive marker of chemotherapy and radiotherapy." (PMID 37092360, 2023). "Some special relationships exist between the gene pair (GATA6 and SPRR3) and the phenotypes of esophageal cancer." (PMID 24743794, 2014). "Another example is involved in the research of esophageal cancer, the combination of the genes GATA6 and SPRR3 may discriminate among normal epithelium, Barrett's dysplasia and Barrett's esophagus associated AC." (PMID 24743794, 2014). "In addition, the decreased expression of DSG3, SPRR3 and MAL, which were all also decreased under conditions of ATRA absence in our experiment, were reported to be related to a poor prognosis of esophageal cancer." (PMID 32556644, 2020).
breast carcinoma (4 papers, 2014 to 2023). "For instance, the performance of the TransMIL algorithm is poor when predicting the expression levels of SPRR3, a marker for terminal squamous cell differentiation linked with tumor progression in early stage breast cancers, and PGAM2, a gene involved in oxidative stress responses." (PMID 37860768, 2023). "However, it has previously been reported that SPRR3 is upregulated in colorectal and breast cancer, suggesting that SPRR3 is associated with malignant tumorigenesis." (PMID 24396461, 2014). "SPRR3 was reported to promote phosphorylation of AKT in tumors such as breast cancer, colorectal tumor, and lung cancer." (PMID 35126350, 2021). "Esophagin, also known as small proline-rich protein 3 (SPRR3), has been demonstrated to be important in the initiation and progression of numerous types of tumor, including colorectal and breast cancer." (PMID 24396461, 2014). "Previously, SPRR3 was demonstrated to be upregulated in colorectal and breast cancer, and these results were in accordance with our findings." (PMID 24396461, 2014).
cervical cancer (4 papers, 2021 to 2025). A primary or metastatic malignant neoplasm involving the cervix. "Studies have found that the molecular typing of pyroptostic‐related genes (PRGs) in cervical cancer can predict prognosis, and the GNAZ/LAG3/IL1B/CA2/SPRR3 risk scoring model has been constructed." (PMID 41025546, 2025). "The S100A6 protein, which was found to be an interacting partner of SPRR3 and SPRR1A in KLK6 high group, has been associated with cells motility and tumor metastasis in cervical cancer cells and lung carcinoma." (PMID 34065672, 2021). "However, the expression of CA2, GNAZ, and SPRR3 did not appear to affect cervical cancer prognosis." (PMID 41025546, 2025).
colorectal cancer (4 papers, 2014 to 2022). A primary or metastatic malignant neoplasm that affects the colon or rectum. "Colorectal cancer (CRC) is an example where the expression of SPRR3 promotes the binding between PCAT18 and miR-759 and therefore restores a portion of the proliferation and invasion capabilities of CRC cells." (PMID 34235216, 2021). "Although the precise regulatory mechanism was not elucidated, we recently showed that ectopic expression of SPRR3 increased AKT phosphorylation in SW480 colorectal cancer cells." (PMID 30850686, 2019).
eczema (2 papers, 2016 to 2023). "Here, the eczema-associated gene SPRR3 shows prominent fold regulation, indicating barrier function-related alterations alongside FLG2, AQP9 and several keratins in vivo." (PMID 37298605, 2023).
glioblastoma (2 papers, 2014 to 2020). The most malignant astrocytic tumor (WHO grade IV). "For example, the expression of SPRR3 (Small Proline Rich Protein 3) was found to be associated with tumor cell proliferation and invasion in glioblastoma multiforme." (PMID 32961999, 2020). "The present study demonstrated that SPRR3 is hypomethylated and upregulated in glioblastoma, and the integrated microarray analysis revealed that SPRR3 hypomethylation was associated with an adverse prognosis." (PMID 24396461, 2014). "However, studies concerning the biological functions of SPRR3 in glioblastoma multiforme (GBM) are limited." (PMID 24396461, 2014).
head and neck squamous cell carcinoma (2 papers, 2023 to 2025). A squamous cell carcinoma that arises from any of the following anatomic sites: lip and oral cavity, nasal cavity, paranasal sinuses, pharynx, larynx, and salivary glands. "In head and neck squamous cell carcinoma, a cornification marker, SPRR3, is associated with cancer cell differentiation." (PMID 40529228, 2025).
oral squamous cell carcinoma (2 papers, 2022). "SPRR3 was identified as a novel diagnostic/prognostic biomarker for oral squamous cell carcinoma (OSCC), and its low expression predicted an unfavorable prognosis in patients with OSCC." (PMID 36510584, 2022).
pancreatic cancer (2 papers, 2023 to 2024). "Herein, we aim to investigate the expression, function, and mechanism of SPRR3 in pancreatic cancer and make an attempt to clarify the underlying mechanism of carcinogenesis of pancreatic cancer and find the effective therapeutic manner to therapy it." (PMID 36685674, 2023). "However, there is no available AD-related information for the ESPL1, KIF20A, SPRR2G, and SPRR3 genes, which instead have associations with various cancers, including adenocarcinoma, medulloblastoma, tongue cancer, and pancreatic cancer, respectively." (PMID 39766348, 2024). "qPCR and western blot assay showed SPRR3 levels were significantly increased in pancreatic cancer tissues compared with normal pancreatic tissues." (PMID 36685674, 2023). "Anchorage-independent growth ability, BrdU labeling, Transwell assay, and in vivo experiment were used to examine the functions of SPRR3 in aggressiveness of pancreatic cancer." (PMID 36685674, 2023). "Our results showed that SPRR3 was significantly overexpressed in pancreatic cancer, which contributed to aggressiveness of pancreatic cancer." (PMID 36685674, 2023). "Secondly, cell function tests showed that SPRR3 elevated anchorage-independent growth ability, BrdU positive cells, and invasion ability of pancreatic cancer cells." (PMID 36685674, 2023). "Altogether, our analysis suggested that upregulation of SPRR3 facilitated the aggressiveness of pancreatic cancer cells." (PMID 36685674, 2023). "Our results showed that SPRR3 was significantly increased in pancreatic cancer, which resulted in poor survival for patients with pancreatic cancer." (PMID 36685674, 2023). "Taken together, our results showed that knockdown of SPRR3 inhibited the aggressiveness of pancreatic cancer cells." (PMID 36685674, 2023). "Consistently, the mRNA and protein expression of SPRR3 were markedly higher in pancreatic cancer cell lines AsPC-1, CFPAC-1, PANC-1, BxPC-3, Capan-1, Capan-2, Hs 766 T, and MIN6 than in normal human pancreatic ductal epithelial cells (HPDECs)." (PMID 36685674, 2023). "For example, the function of SPRR3 in vivo in pancreatic cancer needs to be clarified, and how SPRR3 regulate NF-κB signaling is unclear, and so on." (PMID 36685674, 2023). "SPRR3 expression was positively related with nuclear p65 levels (r = 0.93; P = 0.046), which further supported that SPRR3 facilitated the aggressiveness of pancreatic cancer cells and the activation of NF-κB signaling." (PMID 36685674, 2023). "Further analysis showed that overexpression of SPRR3 contributed to anchorage-independent growth ability, growth rate, and invasion ability of pancreatic cancer cells." (PMID 36685674, 2023). "Firstly, our analysis showed that SPRR3 was significantly increased in pancreatic cancer and closely related with poor survival for patients with pancreatic cancer." (PMID 36685674, 2023). "The analysis showed high levels of SPRR3 predicted poor overall survival and poor disease-free survival for patients with pancreatic cancer." (PMID 36685674, 2023). "Our results showed that anchorage-independent growth ability of SPRR3 downregulating pancreatic cancer cells significantly reduced compared with control cells." (PMID 36685674, 2023). "We also established the stable cell lines with SPRR3 knockdown to explore the function of SPRR3 in the progression of pancreatic cancer." (PMID 36685674, 2023). "Luciferase reporter assay, nucleoplasmic-separation technique, qPCR, and western blot assay were used to investigate the mechanism of SPRR3 regulating aggressiveness of pancreatic cancer." (PMID 36685674, 2023). "Corresponding, knockdown of SPRR3 inhibited the aggressiveness of pancreatic cancer." (PMID 36685674, 2023). "In addition, the invasion ability of pancreatic cancer was significantly reduced in SPRR3-silenced pancreatic cancer cells." (PMID 36685674, 2023). "qPCR and western blot assay were used to determine the expression of SPRR3 in pancreatic cancer." (PMID 36685674, 2023).
pancreatic cancer (continued). "Since NF-κB signaling plays an important role in aggressiveness of pancreatic cancer, we subsequently investigate whether SPRR3 regulated the NF-κB signaling in pancreatic cancer." (PMID 36685674, 2023). "Moreover, BrdU incorporation assay showed that knockdown of SPRR3 dramatically inhibited the growth rate of pancreatic cancer cells." (PMID 36685674, 2023). "Our results extended the mechanisms of pancreatic cancer carcinogenesis and provided evidence that targeting SPRR3 might be an effective strategy to therapy pancreatic cancer." (PMID 36685674, 2023). "Our study provided evidence for a new link of SPRR3 and NF-κB pathway in pancreatic cancer." (PMID 36685674, 2023). "Furthermore, Transwell assay showed that overexpression of SPRR3 promoted the invasion ability of pancreatic cancer cells." (PMID 36685674, 2023). "Moreover, BrdU incorporation assay showed that overexpression of SPRR3 significantly facilitated the growth rate of pancreatic cancer cells." (PMID 36685674, 2023). "Finally, the blockage of NF-κB pathway using NF-κB inhibitor inhibited colonies formed in soft agar, BrdU positive cells, and invaded cells of SPRR3-overexpressing cells, suggesting that activation of NF-κB is essential for SPRR3 regulating aggressiveness of pancreatic cancer cells." (PMID 36685674, 2023). "And targeting SPRR3 might be an effective strategy to therapy pancreatic cancer." (PMID 36685674, 2023). "However, the expression, function, and mechanism of SPRR3 in pancreatic cancer remain unclear." (PMID 36685674, 2023).
psoriasis (2 papers, 2016 to 2021). An autoimmune condition characterized by red, well-delineated plaques with silvery scales that are usually on the extensor surfaces and scalp. "The upregulated OS genes SPRR3 and SPRR2A are the encrypt for the Late Cornified Envelope (LCE) protein present in cornified cell envelope (CE) in both psoriasis and atopic dermatitis; the expression of these genes is linked to keratinocyte terminal differentiation both in vivo and in vitro." (PMID 34925353, 2021).
allergic asthma (1 paper, 2021). A asthma with a basis in a pathological type I hypersensitivity reaction. "Our study shows that SPRR3 acts as a key upstream modulator in airway epithelial inflammation and Th2 responses, potentially serving as a novel therapeutic target for the treatment of allergic asthma." (PMID 35126350, 2021).
asthma (1 paper, 2021). "In this study, bioinformatics analysis of GEO databases revealed that SPRR3 gene expression was significantly increased in asthma." (PMID 35126350, 2021). "While the roles of SPRR1B and SPRR3 in asthma are unclear, it has been shown that the members of the SPRRs family SPRR2A and SPRR2B are upregulated in an IL-13-dependent manner in an allergen-induced asthma model." (PMID 35126350, 2021). "Here,we use HDM to establish an asthma mouse model, and confirmed via quantitative PCR that the mRNA expression of SPRR3 was increased in the lung tissues of asthmatic mice." (PMID 35126350, 2021). "This study reveals the regulatory role of SPRR3 in allergic airway inflammation, identifying this protein as a potential novel therapeutic target for asthma." (PMID 35126350, 2021). "Therefore, further work on SPRR3-knockout mice is essential to validate the findings of the current study and clarify the mechanism of the SPRR3-mediated PI3K/AKT/NF-κB pathway in more detail in asthma." (PMID 35126350, 2021). "Whether SPRR3 regulates other pathological processes of asthma through the PI3K/AKT/NF-κB signaling pathway remains unclear." (PMID 35126350, 2021).
atherosclerosis (1 paper, 2017). A disease characterized by the build-up of fatty material and calcium deposition in the arterial wall resulting in partial or complete occlusion of the arterial lumen. "Sprr3-/- mice were primarily evaluated on the ApoE-/- background to induce hyperlipidemia and atherosclerosis progression." (PMID 28886156, 2017). "It was previously shown that Sprr3 ablation alone is not sufficient to generate significant atherosclerosis due to low blood lipid levels." (PMID 28886156, 2017).
chronic obstructive pulmonary disease (1 paper, 2021). A chronic and progressive lung disorder characterized by the loss of elasticity of the bronchial tree and the air sacs, destruction of the air sacs wall, thickening of the bronchial wall, and mucous accumulation in the bronchial tree. "Other evidence indicated that SPRR3 was upregulated in the airway epithelium of smokers, which could contribute to the development of chronic obstructive pulmonary disease (COPD)." (PMID 35126350, 2021).
coeliac disease (1 paper, 2008). "Staining for SPRR3 was increased in the untreated coeliac disease samples when compared to the gluten-free diet samples in 4 out of 5 cases." (PMID 18691394, 2008). "The increased expression of transglutaminase 2 found in the enterocytes and basement membrane in active coeliac disease could cross-link with SPRR3 to form a cornified envelope-like barrier." (PMID 18691394, 2008). "The up-regulation of SPRR3 in active coeliac disease may be a defensive response to protect the mucosa from any further damage caused by the ingestion of gluten." (PMID 18691394, 2008). "While SPRR3 is clearly upregulated in enterocytes in the coeliac gut, it is not clear whether this response is gluten-specific or the result of the architechtural changes typical of coeliac disease." (PMID 18691394, 2008).
glioma (1 paper, 2014). A benign or malignant brain and spinal cord tumor that arises from glial cells (astrocytes, oligodendrocytes, ependymal cells). "Kaplan-Meier survival curves, according to the methylation level of SPRR3 in 42 frozen glioma tissues, demonstrated that SPRR3 hypomethylation was associated with a poor clinical outcome in GBM patients." (PMID 24396461, 2014). "The OS time was measured through Kaplan-Meier survival curve analysis and the results revealed that glioma patients with a low methylation level of SPRR3 had significantly lower progression-free survival rates (P=0.010) and OS times (P=0.007) than patients with a high methylation level." (PMID 24396461, 2014). "The results of the immunohistochemical staining demonstrated that SPRR3 was upregulated in the tissue samples of more than half of the GBM patients (72.7%) and the methylation level of SPRR3 was correlated with the clinical outcome in glioma patients validated by DNA methylation profile analysis." (PMID 24396461, 2014).
intraepithelial neoplasia (1 paper, 2014). A precancerous neoplastic process that affects the squamous, glandular, or transitional cell epithelium without evidence of invasion. "The expression of cystatin A, involucrin and SPRR3 was remarkably decreased during the malignant transformation from normal epithelium to low-grade intraepithelial neoplasia (LGIN) or high-grade intraepithelial neoplasia (HGIN)." (PMID 24796531, 2014).
keratinocyte carcinoma (1 paper, 2023). A skin cancer arising from the keratin-producing cells of the epidermis. "Conversely, keratinocyte cancer cells stained with an epithelial differentiation marker (SPRR3) were located at the tumor core, consistent with the negative correlation between these programs suggested by the survival analysis." (PMID 37853464, 2023).
keratoconus (1 paper, 2026). A degenerative, structural disorder of the eye, characterized by a cone-shaped protrusion of the cornea. "Proteins with potential roles in maintaining epithelial integrity, such as Annexin A5, mucin-like protein 1, and small proline-rich protein 3, were reduced in keratoconus tears, consistent with previous reports of compromised epithelial barrier function in these patients." (PMID 41601845, 2026).
liver cirrhosis (1 paper, 2018). "Specific loci, including collagen 1A1, secreted phosphoprotein 1, SPRR3 and TNFSF15, have been confirmed to be hypomethylated, resulting in the up-regulation of these genes in patients with liver cirrhosis of various etiologies." (PMID 30038293, 2018).
melanoma (1 paper, 2017). A malignant, usually aggressive tumor composed of atypical, neoplastic melanocytes. "From this, we identified a panel of 6 genes, ALDH1A1, HSP90AB1, KIT, KRT16, SPRR3 and TMEM45B whose expression values discriminated metastatic from primary melanoma (87% classification accuracy)." (PMID 29229936, 2017).